NUP155 (nucleoporin 155)
Diseases named in the same sentence as NUP155 in open-access papers (continued):
Sharing a sentence is not in itself a finding about the gene and the disease.
tumor (7 papers, 2019 to 2024). "Furthermore, NUP155 was significantly and positively correlated with DNA methylation, tumor mutational burden, microsatellite instability, and stemness score in most cancers." (PMID 38504158, 2024). "In particular, NUP155 expression was positively correlated with advanced tumor stage in ACC, KICH, KIRP, and LIHC." (PMID 38504158, 2024). "NUP155 is involved in mitotic arrest mediated by the novel anti-tumor drug NP-10 and regulates mRNA translation for the cell cycle protein-dependent kinase inhibitor p21." (PMID 38504158, 2024). "Analysis of NUP155 expression can aid in selecting anti-tumor drugs in clinical practice, especially for drug-resistant tumors." (PMID 38504158, 2024). "The CCK-8 assay results revealed that transfection with si-NUP155 significantly decreased tumor cell proliferation." (PMID 38504158, 2024). "Additionally, NUP155 was also found to be involved in TIME and closely associated with tumor infiltrating immune cells and immunoregulation-related genes." (PMID 38504158, 2024). "Thus, our study highlights the potential value of NUP155 as a biomarker in the assessment of prognostic prediction, tumor microenvironment and immunotherapeutic response in pan-cancer." (PMID 38504158, 2024). "Analysis of the xCell dataset and the TISCH dataset revealed that NUP155 upregulation may modulate the tumor microenvironment status by upregulating the levels of Tregs and regulating the balance of Th1 and Th2 cells." (PMID 38504158, 2024). "The correlation of NUP155 expression with DNA promoter methylation, somatic mutations, tumor mutational burden (TMB), microsatellite instability (MSI), tumor stemness, mismatch repair (MMR), TIME, infiltrating immune cell profile, and immune-related biomarkers was further investigated." (PMID 38504158, 2024). "This systematic pan-cancer analysis suggested that NUP155 was differentially expressed between non-cancerous and cancer tissues and that NUP155 dysregulation is associated with tumor staging and can be used to predict the prognosis." (PMID 38504158, 2024). "The establishment of the sensitivity of tumors with differential expression levels of NUP155 to anti-tumor drugs may guide tumor treatment." (PMID 38504158, 2024). "However, the role of NUP155 in tumor physiology and the tumor immune microenvironment (TIME) has not been previously examined." (PMID 38504158, 2024). "Thus, there is growing evidence linking NUP155 to tumor development." (PMID 38504158, 2024). "Thus, NUP155 expression was correlated with DNAss and RNAss in several tumors and may potentially promote the activation of tumor stem cells and facilitate tumor recurrence and proliferation." (PMID 38504158, 2024). "The ESTIMATE score revealed a negative correlation between NUP155 expression and the levels of stromal and immune cells in the tumor microenvironment of 15 different cancer types." (PMID 38504158, 2024). "The NUP155 mRNA expression levels varied between tumor and non-cancerous tissue in 29 cancers (samples for which non-cancerous tissue data were not available were excluded)." (PMID 38504158, 2024). "However, previous studies have not examined the role of NUP155 in tumor physiology and TIME in pan-cancer datasets." (PMID 38504158, 2024).
cancer (6 papers, 2019 to 2024). A tumor composed of atypical neoplastic, often pleomorphic cells that invade other tissues. "Studies have shown that NUP155 is associated with the occurrence of a variety of cancers, and it has been found to have mutations in a variety of tumors, such as cervical adenocarcinoma, endometrial cancer, melanoma cancer." (PMID 39720592, 2024). "Cox regression analysis of TCGA dataset revealed that NUP155 upregulation is a risk factor for OS in 13 types of cancer." (PMID 38504158, 2024). "Thus, NUP155 upregulation is associated with poor prognosis in most cancers." (PMID 38504158, 2024). "Comprehensive analysis of the correlation between NUP155 expression and the degree of immune cell infiltration in various cancer types was performed using the xCell database." (PMID 38504158, 2024). "Recent studies have reported that NUP155 expression is correlated with the prognosis of various cancers." (PMID 38504158, 2024). "The expression of NUP155 exhibited varying degrees of correlation with DNAss and RNAss in different cancer types." (PMID 38504158, 2024). "In this study, gene co-expression analysis was performed to investigate the correlation between NUP155 expression and immune-related genes in various cancers." (PMID 38504158, 2024). "After inhibition of NDC1, the protein expression of NDC1 in cancer cells was remarkably reduced, and the protein expression of NUP155 remained unchanged." (PMID 39720592, 2024). "Among these eight cancers, NUP155 expression was negatively correlated with both stromal and immune scores in GBM, STES, STAD, and SKCM." (PMID 38504158, 2024). "Next, this study examined the prognostic value of NUP155 in different cancer types using survival analyses." (PMID 38504158, 2024). "This study aimed to comprehensively analyze the differential expression, prognostic value, and biological function of NUP155 in different cancer types." (PMID 38504158, 2024). "This study aimed to comprehensively analyze the expression pattern, prognostic value, and immunological functions of NUP155 across 33 types of cancer." (PMID 38504158, 2024). "This study comprehensively investigated the expression, immunological function, and prognostic significance of NUP155 in different cancer types." (PMID 38504158, 2024). "After knockdown of NUP155, the protein expression of A549 and H1299 in cancer cells decreased, and the invasion, proliferation and migration ability of cancer cells were also weakened." (PMID 39720592, 2024). "NUP155 can also serve as a predictive biomarker of immunotherapeutic response in some cancers." (PMID 38504158, 2024). "Overexpression of NUP155 manifested the opposite in cancer cells." (PMID 39720592, 2024). "The cBioPortal database was used to investigate the NUP155 alterations in pan-cancer." (PMID 38504158, 2024). "Additionally, NUP155 upregulation was strongly correlated with advanced pathological or clinical stages and poor prognosis in several cancers." (PMID 38504158, 2024). "NUP155 expression was correlated with MMR genes in almost all cancers." (PMID 38504158, 2024). "In the course of reviewing the literature, we found NUP155 work in a variety of cancers." (PMID 39720592, 2024). "The results of this study suggest that NUP155 plays a crucial role in cancer immunity." (PMID 38504158, 2024). "Bioinformatics analysis revealed that NUP155 was upregulated in 26 types of cancer." (PMID 38504158, 2024). "NUP155 is upregulated in most cancer types but is downregulated in LAML and TGCT." (PMID 38504158, 2024). "Indeed, we were able to co-immunoprecipitate HDAC4 and Nup155 confirming an interaction of both proteins also in liver-derived cancer cells." (PMID 31089132, 2019). "Additionally, DNA methylation, TMB, MSI, cancer stemness, TIME, and immune cell infiltration may be correlated with NUP155 dysregulation in cancer." (PMID 38504158, 2024).
cancer (continued). "Hence, we hypothesized that the correlation between NUP155 expression, ICP-encoding gene expression, and the degree of immune cell infiltration affects the response of patients with cancer to immunotherapy." (PMID 38504158, 2024). "Furthermore, the landscape of NUP155 copy number variation (CNV) in pan-cancer was examined." (PMID 38504158, 2024). "Thus, NUP155 may mediate the effects of immunotherapy in patients with cancer by regulating TIICs and ICPs." (PMID 38504158, 2024). "The findings of this study indicate a strong correlation between NUP155 expression and the levels of TMB and MSI in various cancer types." (PMID 38504158, 2024). "The differential expression of NUP155 between cancer and non-cancerous tissues was the most pronounced in DLBC and THYM." (PMID 38504158, 2024). "A link between a scaffold Nup and transcriptional regulation of a gene involved in mRNA translation, as shown here for Nup155 has, to the best of our knowledge, not been described before in human cancer." (PMID 31089132, 2019). "Thus, this study examined the correlation between NUP155 expression and TIME in pan-cancer." (PMID 38504158, 2024).
infection (5 papers, 2013 to 2025). The state of being infected such as from the introduction of a foreign agent such as serum, vaccine, antigenic substance or organism. "Two distinct effects on infection are observed when CypA is depleted in Nup153- and Nup155-knockdown cells." (PMID 37355754, 2023). "There were, however, a number of differences in Nup requirements for HIV-1WT infection in RANBP2∆Cyp cells, including a dramatic increase in sensitivity to NUP155 knockdown, and decreased sensitivity to NUP107, NUP93, and RANBP2 depletion." (PMID 39853118, 2025). "Curiously, the effects of CPSF6 depletion were reminiscent of the effects of NUP155 depletion, in that they similarly reduced the respective CsA-induced enhancement or inhibition of HIV-1WT, HIV-1A92E, and HIV-1N57S infection." (PMID 30084827, 2018). "We observed that NUP98 protein levels were decreased both in SupT1 and HEK293T cell types upon HIV-1 NL4.3 infection by 4.7- and 1.5-fold, respectively (respectively), whereas the protein levels of other NUPs such as NUP62, NUP155, NUP133, NUP107, and NUP85 remained unaffected." (PMID 38449868, 2024). "Nup155 is a non-FG Nup in the Nup93-subcomplex that we previously noted N74D HIV-1 to be more dependent for infection than WT HIV-112." (PMID 37355754, 2023). "The CsA dependence of HIV-1A92E infection in HeLa cells was exaggerated by some Nup knockdowns (e.g. NUP93, NUP205, NUP54, NUP153) while other knockdowns reduced or eliminated the enhancing effects of CsA (e.g. NUP98, NUP107, NUP155)." (PMID 30084827, 2018). "Infection by HIV-1N57S was strongly inhibited by CsA in HT1080 cells and Nup depletions partly (e.g. NUP62, NUP54, NUPL1) or nearly completely (e.g. NUP155, NUP205) abolished this CsA sensitivity." (PMID 30084827, 2018). "While WT HIV-1 infection of HeLa cells was not impeded by NUP155 depletion, HIV-2 and SIVmac infection was inhibited." (PMID 30084827, 2018). "Moreover, the striking ability of CsA to strongly inhibit HIV-1N57S infection in HT1080 cells (that was not evident in HeLa cells) was nearly completely abolished by NUP155 depletion." (PMID 30084827, 2018).
cardiac disease (1 paper, 2020). "Ultimately, characterization of the systems biology level effects of these NUP155 variants will be critical to understanding and defining a novel determinant of cardiac disease etiology, as well as develop the broader emerging paradigm of nups in development and disease." (PMID 32118046, 2020).
NUP155 also shares sentences with these, for which no sentence is quoted: cervical adenocarcinoma (1 paper); cervical squamous cell carcinoma (1); clear cell renal cell carcinoma (1); colon cancer (1); Duchenne muscular dystrophy (1); esophageal carcinoma (1); Fanconi anemia (1); glioblastoma multiforme (1); glioma (1); head and neck squamous cell carcinoma (1); leukemia (1); lung adenocarcinoma (1); paraganglioma (1); pheochromocytoma (1); sarcoma (1); testicular germ cell tumor (1); thyroid carcinoma (1); uveal melanoma (1).